BRAF (B-Raf proto-oncogene, serine/threonine kinase)
Diseases named in the same sentence as BRAF in open-access papers (continued):
Sharing a sentence is not in itself a finding about the gene and the disease.
melanoma (continued). "Almost 60% of melanomas are reported to be BRAF mutant, and mutations in this gene are also present in non-Hodgkin’s lymphoma, colorectal cancer, papillary thyroid carcinoma, NSCLC, glioblastoma as well as inflammatory diseases." (PMID 31426419, 2019). "In BRAF-mutated melanoma models, combined BRAF and MEK inhibition significantly improved clinical outcomes in patients with metastatic melanoma." (PMID 31652660, 2019). "Concurrent inactivation of PTEN and RB1 have previously been described as a mechanism for loss of BRAF/MEK dependence in BRAFV600E mutated melanomas and the cell cycle progression pathway including RB1 have been associated to BRAF inhibitors resistance." (PMID 30899440, 2019). "Physiologically, proinflammatory cytokines activate ITCH to maintain BRAF activity and to promote proliferation and invasion of melanoma cells, whereas the ubiquitination-deficient BRAF mutant displays compromised kinase activity and reduced tumorigenicity." (PMID 31015455, 2019). "Another mutation predictive of response to EGFR-inhibiting therapy is BRAF, which is associated with a very poor prognosis particularly in colorectal cancer and melanoma." (PMID 31635038, 2019). "Specifically, for example, the “triple wild-type” melanoma which lacks mutations in either of the genes usually found mutated - BRAF, NRAS, and NF1 genes." (PMID 31731811, 2019). "In treatment monitoring, single gene analysis require identification of an early event in the tumour and for melanoma BRAF/NRAS hotspot mutations are good candidates." (PMID 31767937, 2019). "Unfortunately, sorafenib has not only demonstrated minimal efficacy in BRAF-mutated melanomas but has had significant side effects." (PMID 30975211, 2019). "One of the most prevalent drivers in melanoma progression is mutated BRAF, identified in more than 40% of patients suffering from this cancer." (PMID 31877948, 2019). "Almost half of all melanomas are driven by mutations in the v-Raf murine sarcoma viral oncogene homolog B (BRAF) with BRAFV600E being the most prevalent mutation." (PMID 30987166, 2019). "The mutation status of the BRAF gene was included in the investigation of patients with melanoma in more recent periods." (PMID 31138295, 2019). "Acquisition of a BRAF fusion has recently been described as a novel mechanism of acquired resistance to vemurafenib in a patient with BRAF V600E melanoma, underlining the key role of this oncogenic activation in cancer survival." (PMID 31731495, 2019). "BRAF mutation that was first identified in malignant melanoma by Davies and colleagues in 200231 is the most prevalent type of genetic alteration in thyroid cancer and has been widely investigated." (PMID 30635590, 2019). "Two of these neoantigens (a 10mer and an 11mer; LUAD 26 and LUAD 31) contained the oncogenic driver mutation BRAF N581I, a hotspot mutation previously reported to recurrently occur in melanoma and colorectal cancer." (PMID 30744692, 2019). "Among 52 consecutive BRAF V600 mutated melanoma patients submitted to DT in our center, 12 (23%) developed immune related skin lesions (IRSLs): 8 panniculitis and 4 vitiligo." (PMID 30939167, 2019). "The data showed that BRAF mutations were present in 8% (107/1339) of mucosal melanoma, 63% (67/107) were located on the V600 codon, and 37% (40/107) on another codon." (PMID 31398831, 2019). "In the present study, the aggressive BRAF-mutated A375 human melanoma cell line was used to pave the way for a more effective therapeutic strategy." (PMID 31783660, 2019). "On the other hand, BRAF-mutated melanoma cells inoculated in mice or cultured in vitro have pointed to the role exerted by tumor-intrinsic factors on the immune system controlling tumor growth." (PMID 31817719, 2019).
melanoma (continued). "MEK is hyper‐activated in over 90% of melanomas, and BRAF harbours activating mutations in approximately 50% of melanomas." (PMID 30277012, 2019). "This shift in the balance between inhibitory and stimulatory NK cells ligands on BRAFMUT melanoma cell lines caused by BRAF inhibition regulated NK cells function." (PMID 31134073, 2019). "Approximately half of cutaneous melanomas harbor driver gene mutations, such as BRAF mutations, depending on the type of melanoma and the patient’s degree of sunlight exposure." (PMID 31817947, 2019). "Such polymorphisms are responsible for the gender predisposition regarding BRAF mutation of melanomas in humans." (PMID 30893857, 2019). "BRAF inhibitors (BRAFi) target selectively the BRAF V600E/K genetic alteration and are widely used to treat melanoma patients harboring BRAFV600 mutation." (PMID 31354491, 2019). "Given the unclear optimal front‐line treatment for patients with advanced BRAF V600 mutated melanoma, we retrospectively compared the overall survival of these patients with front‐line aPD‐1, niv/ipi, or BRAF/MEKi." (PMID 31677253, 2019). "Among melanoma patients, the co-existence of hTERT promoter and BRAF/NRAS mutations were related to 2-fold reduced disease-free and 5-fold reduced melanoma-specific survival." (PMID 31186051, 2019). "Remarkably, treatment with PLX-4270 (BRAF inhibitor) activates tumor-associated fibroblasts to induce ECM remodeling that activates integrin β1/FAK/Src signaling in melanoma cells." (PMID 31067787, 2019). "Metastatic melanoma, including the BRAF-mutated subgroup, is very resistant to both traditional chemotherapy and targeted therapy, leaving most of the patients undergoing resistance without any other therapeutic strategies." (PMID 30362384, 2019). "Using BRAF-mutant melanoma cell lines as the prototype, we report on a joint theoretical and experimental investigation of the cell-state transition dynamics associated with BRAF inhibitor drug tolerance." (PMID 31166947, 2019). "Of these, 2283 patients’ melanomas harbored a documented BRAF V600 mutation, and 1356 of these patients had documentation of systemic therapy for advanced disease at the clinical sites." (PMID 31677253, 2019). "In the same year, Helen Davies described a high frequency of BRAF mutation in melanoma, which brought new insight in melanoma etiology." (PMID 30884760, 2019). "Oncogenic driver mutations in melanoma involve BRAF (~50%), NRAS, KRAS and HRAS (~25%) and NF1 (~15%)." (PMID 31058846, 2019). "Over the years, small molecules targeting BRAFV600E have been discovered to be very effective melanoma drugs, but they are known to cause the BRAF paradox." (PMID 31307243, 2019). "Mutations occurring outside codon 600 were seen in 43 tumors (23% of BRAF-mutated melanomas or 9.6% of melanomas)." (PMID 31277584, 2019). "The molecular diagnosis based only on genetic alterations can lead to treatments with unpredictable responses, depending on the tumour location, such as the tumour response in melanomas versus colon carcinomas with BRAF mutations." (PMID 30667539, 2019). "Coexisting BRAF and activating RAS mutations were observed in none of 147 melanomas with a class-1 BRAF mutation, 2 (14%) of 14 melanomas with a class-2 BRAF mutation, and 5 (23%) of 22 melanomas with a class-3 BRAF mutation." (PMID 31277584, 2019). "PIK‐75 was then used alone or in combination with vemurafenib, the first BRAF inhibitor approved for patients with melanoma harboring BRAF mutations." (PMID 31115969, 2019). "Patients with melanoma bearing such a cancer‐driving mutation can be effectively treated with a BRAF inhibitor (BRAFi), for example, vemurafenib and dabrafenib." (PMID 30582770, 2019). "Activating mutations in the BRAF gene have also been identified in non-melanoma tumors, including thyroid, colorectal carcinomas, lung cancer, and hairy cell leukemia, and were linked to the glycolytic phenotype in both in vitro and in vivo cancer models." (PMID 30487597, 2019).
melanoma (continued). "Although most studies on the role of BRAF in melanoma have focused on the BRAF V600E mutation, several other mutations in the BRAF gene have been identified, and the biochemistry of the various altered BRAF proteins has been shown to vary substantially." (PMID 31398831, 2019). "BRAF mutations have been identified in melanoma and colorectal cancer, but is rarely reported in NPC." (PMID 31664962, 2019). "Melanoma cells bearing secondary NRASQ61K mutation are more vunerable to dvelop Vemurafenib resistance than cells with primeray BRAF mutations." (PMID 31578454, 2019). "Inhibitors of the MAP-kinase pathway have become a mainstay of melanoma treatment, particularly in the setting of activating BRAF mutations." (PMID 31886081, 2019). "While developed from data from patients both with and without the BRAF-V600E mutation, this signature performed best for BRAF-V600E melanoma patients." (PMID 31672130, 2019). "Another multicenter, open-label phase II trial examined the response of BM from BRAF-mutated melanoma to vemurafenib." (PMID 31803366, 2019). "Combinations of MCL-1 inhibitors with BRAF inhibitors also caused only minimal additional melanoma cell killing over each drug alone, whilst combinations with the proteasome inhibitor bortezomib was more effective in multiple cell lines." (PMID 31019203, 2019). "This discovery makes RAC1 the third most commonly mutated (somatic) proto-oncogene in melanoma after BRAF and NRAS." (PMID 31027363, 2019). "In this study we applied SynGeNet, a computational drug combination prediction method, to four subtypes of melanoma based on genomic classification of major driver events, including mutations in BRAF, NRAS, NF1, and TWT tumors." (PMID 30820351, 2019). "In melanoma, for example, mutations in the BRAF protein kinase, which are found in ∼ 50% of tumors, drive the hyper-activation of MAPK signaling." (PMID 31727958, 2019). "Previous studies have revealed that melanoma is associated with inter-tumor heterogenous BRAF status in about 4%–25% of patients." (PMID 31817947, 2019). "The capability in the identification of rare and low-frequency mutations in the main genes involved in melanoma (BRAF and NRAS genes) was verified and integrated with the results deriving from other oncogenes and tumor suppressor genes." (PMID 31547467, 2019). "Cobimetinib was FDA approved in 2015 for the use in combination with vemurafenib for the treatment of advanced melanomas with BRAF V600E or V600K mutations." (PMID 30975211, 2019). "BRAF V600 mutations are relevant therapeutically in melanoma, enabling treatment with BRAF and MEK inhibitors." (PMID 30995742, 2019). "Even therapies specifically targeting prevalent tumor mutations, such as the BRAF V600E mutation in melanoma and a variety of EGFR point mutations in lung cancer, only lead to relatively short-lived tumor responses." (PMID 30925887, 2019). "In this sense, in melanoma, the analysis of circulating DNA from tumour has been focused mainly on the detection of driver gene mutations, e.g. BRAF and NRAS." (PMID 30900145, 2019). "The data reported in this study suggest that in visceral metastases of malignant melanoma BRAF- or NRAS-mutant allele fractions are rather heterogeneous and are quite difficult to predict based on data from the primary tumor." (PMID 31391014, 2019). "Over 50% of melanoma patients carry a mutation in their BRAF gene, with the V600E (valine to glutamic acid) missense mutation being responsible for 80–90% of BRAF mutations." (PMID 30909892, 2019). "In order to assess if neuregulin-induced pErbB3 activation occurs also in the clinical setting we decided to carry out a clinical study in BRAF mutated melanoma patients undergoing standard dual therapy with MAPK inhibitors." (PMID 31557826, 2019).
melanoma (continued). "Large clinical trials of BRAF inhibitors in adults with BRAFV600E mutated melanoma resulted in tumor response and prolonged progression free survival (PFS) and OS." (PMID 30728904, 2019). "Specific focus will be put on melanoma and thyroid cancer, which share the property of being associated with a high prevalence of BRAF mutations." (PMID 31762942, 2019). "Of these, 50% of melanomas harbor mutations in BRAF, mainly at codon 600, which results in the continuous activation of the MAPK pathway." (PMID 30832692, 2019). "The most used targeted therapies act on the MAPK pathway, which is mutated in NRAS and BRAF in about 25 and 60% of melanoma patients, respectively." (PMID 31013837, 2019). "In total, 8/58 patients in the as-treated population (14%) had a confirmed OR: 3 had melanoma (2 with BRAF mutations) and 5 had kidney cancer, including 1 who had a CR." (PMID 31439037, 2019). "The proto-oncogene BRAF is mutated in approximately 50% of malignant melanomas, and BRAF-mutant melanoma is associated with a higher rate of CNS involvement (24%) compared with BRAF wild type melanomas (12%)." (PMID 31803366, 2019). "Previous studies have divided melanomas into four groups based on the driver mutation: BRAF-mutant, NRAS-mutant, NF1-mutant and triple-wild-type." (PMID 31322504, 2019). "By far the most important mutated oncogene in melanoma is the v-Raf murine sarcoma viral oncogene homolog B (BRAF), with the BRAF V600E mutation being the most relevant mutation representing 40–50% of all mutated melanomas and 80% of the BRAF-mutated tumors." (PMID 30987166, 2019). "Vemurafenib was the first specific kinase inhibitor approved for therapy of advanced melanomas harboring BRAF-activating mutations, followed by dabrafenib and encorafenib." (PMID 30934534, 2019). "Melanoma samples carrying BRAF or RAS mutations presented significantly higher expression levels of ZEB1-AS1 (P-value < 0.001 and P-value < 0.05, respectively) when compared to the Triple Wild-Type group." (PMID 31383874, 2019). "On the other hand, Flux Balance Analysis predicts a higher tumor growth rate in BRAF mutated melanoma samples." (PMID 31076580, 2019). "In BRAFv600 mutated melanoma patients upon BRAF inhibitors, a hypercoagulable state correlates with prognosis, while a down-regulation of the hemostatic parameters is observed in patients responders as compared to non responders." (PMID 31467489, 2019). "In BRAF V600E-mutated melanomas, such therapeutical approaches inhibit the activity of key members of the MAPK pathway, such as BRAF and MEK." (PMID 31835364, 2019). "For instance, a phase II trial of dabrafenib, trametinib, and nivolumab in BRAF-mutated advanced melanoma patients showed an overall response rate 91% with relatively small proportion of patients that discontinued the study due to drug toxicity." (PMID 31340499, 2019). "Our data provide the first in vitro observation that BRAF/MEK inhibitors decrease TF in BRAFv600e mutated melanoma cells thus inhibiting the coagulation cascade, adding one more piece of evidence to the complex relationship between coagulation and cancer." (PMID 31467489, 2019). "Based on the genomic DNA analysis, melanoma are categorized into four major subtypes that include BRAF-mutant, NRAS-mutant, NF1-deleted/mutated or triple negative melanoma." (PMID 31217906, 2019). "al. examined the role of the BRAF mutation in melanoma by using the first specific inhibitor of the BRAF V600E mutation, called Vemurafenib." (PMID 31531096, 2019). "In summary, the acquisition of the dedifferentiated cell state at the time of vemurafenib relapse is occurring at least as frequently as MAPK pathway mutations in BRAF mutant melanoma." (PMID 30824837, 2019).
melanoma (continued). "It has been reported that IGFBP7 inhibits the BRAF-MEK-ERK pathway in an autocrine or paracrine manner and causes apoptosis in BRAF mutation-positive melanoma cells." (PMID 31183073, 2019). "The obtained results validate the application of combination therapy directed against EGFR and MET in melanoma cells resistant to treatment with inhibitors of mutated BRAF." (PMID 31877948, 2019). "According to successful experience in BRAF inhibitors targeting BRAF mutant cancers like melanoma, two patients of recurrent CPs with BRAF V600E mutation were subscribed with BRAF/MEK inhibitors." (PMID 30616515, 2019). "The general capability of the NGS panel to detect rare BRAF mutations was also verified by melanoma samples analysis." (PMID 31547467, 2019). "In detail three BRAF-mutated melanoma cell lines (WM266, WM115 and LOX IMVI) were treated with vemurafenib (0.5 μM) for different times (2 h, 8 h and 24 h)." (PMID 31557826, 2019). "Nevertheless, the detection rate of ctDNA in melanoma patients and concordance of mutations between plasma and tissue still requires further study, especially beyond detection of BRAF mutations." (PMID 30312528, 2019). "Dabrafenib is also an extremely potent inhibitor of V600E-mutated BRAF, which has shown efficacy in melanoma and CRC both in vitro and in vivo." (PMID 30975211, 2019). "The BRAF activating mutation is present in 40–50% of melanomas, providing an important therapeutic target that can be clinically exploited by inhibiting the MAPK/ERK signaling pathway." (PMID 31921863, 2019). "Further, the predictive values of V600E and V601E mutations have been demonstrated for the use of RAF kinase inhibitor (vemurafenib) and MEK inhibitor (trametinib), respectively, in BRAF-mutated melanomas." (PMID 31635038, 2019). "Particular attention has been devoted over the last years to unravel mechanisms at the basis of adaptive/non genetic resistance occurring in BRAF mutated melanomas upon treatment with to MAPKi." (PMID 31557826, 2019). "DHODH dependency has also been reported in melanoma harboring the BRAF V600E mutation, acute myeloid leukemia, PTEN mutant cells, and K-RAS mutant pancreatic tumor cells." (PMID 31108873, 2019). "The BRAF is one of the important proto-oncogenes which gets mutated in case of melanoma and its lower expression attributed to the lowering of melanoma." (PMID 31126298, 2019). "AXL inhibition is shown to be pivotal in overcoming intrinsic or acquired resistance to BRAF/MEK inhibitors by melanoma harboring NRAS and BRAF mutations." (PMID 30651547, 2019). "This study categorizes the range, frequency, coexisting driver mutations and clinical characteristics of the three classes of BRAF mutations in a large cohort of melanomas in a clinical diagnostic setting." (PMID 31277584, 2019). "For example, in BRAF(V600)-mutated melanoma, resistance to anti-BRAF and anti-MEK therapies, can be overturned by altering EIF4F complex activity by using EIF4A inhibitors." (PMID 30072418, 2019). "Laura Held studied proliferative activity, chromosomal defects, and tumor mutation via gene hybridization, and assessed BRAF in differentiating blue nevi from melanomas." (PMID 31531096, 2019). "In our study, IGF2as was upregulated in BRAF-mutated advanced melanoma patients compared to healthy donors, and its high expression level was linked to more favorable survival." (PMID 31231466, 2019). "Mechanisms underlying the stroma-mediated innate resistance to the BRAF inhibitor have also been addressed using BRAF-mutant melanoma cells in other studies." (PMID 31067787, 2019). "This is due to activation of stromal fibroblast, elevation of matrix production, and remodeling leading to elevated integrin β1/FAK/Src signaling in melanoma cells associated with BRAF inhibitor, PLX4720." (PMID 30680600, 2019).